SCMH1 (Scm polycomb group protein homolog 1)
Description:
Associates with Polycomb group (PcG) multiprotein complexes; the complex class is required to maintain the transcriptionally repressive state of some genes.
Synonyms: Scml3
Tractability: PROTAC: ubiquitination databases record sites on it.
Gene: Protein-coding gene on chromosome 1 (41,027,202 to 41,242,306, reverse strand). Ensembl gene ENSG00000010803.
Subcellular location: Nucleus
Subcellular location (Human Protein Atlas): Nucleoplasm; Cytosol; Nuclear bodies
Pathways (Reactome):
Metabolism of proteins: SUMOylation of DNA damage response and repair proteins; SUMOylation of DNA methylation proteins; SUMOylation of RNA binding proteins; SUMOylation of chromatin organization proteins; SUMOylation of transcription cofactors
Cellular responses to stimuli: Oxidative Stress Induced Senescence
Developmental Biology: Differentiation of naive CD4+ T cells to T helper 2 cells (Th2 cells)
Gene expression (Transcription): RUNX1 interacts with co-factors whose precise effect on RUNX1 targets is not known
Signal Transduction: Regulation of PTEN gene transcription
Gene Ontology:
Molecular function: protein binding; chromatin binding; histone binding
Biological process: heterochromatin formation; negative regulation of DNA-templated transcription; regulation of DNA-templated transcription
Cellular component: nucleoplasm; nucleus
Genetic constraint (gnomAD): Loss-of-function variants: 33 observed, 67.43 expected, observed/expected ratio (o/e) 0.49, 90% interval 0.37 to 0.65. The upper end of that interval is the gene's LOEUF score, 0.65, which puts it in group 2 of 6, group 1 being the genes least tolerant of losing a copy. Missense variants: 586 observed, 836.36 expected, observed/expected ratio (o/e) 0.7, 90% interval 0.65 to 0.75. Synonymous variants: 282 observed, 312.17 expected, observed/expected ratio (o/e) 0.9, 90% interval 0.82 to 1.
Homologues: Orthologues: macaque SCMH1 (99% identical), chimpanzee SCMH1 (95% identical), rat Scmh1 (92% identical), dog SCMH1 (91% identical), mouse Scmh1 (89% identical), pig SCMH1 (87% identical), rabbit SCMH1 (84% identical), guinea pig SCMH1 (81% identical), tropical clawed frog scmh1 (70% identical), Drosophila melanogaster l(3)mbt (16% identical), Drosophila melanogaster Sfmbt (14% identical), zebrafish scmh1 (14% identical), and 2 more. Paralogues in human: SCML2 (47% identical), SCML4 (27% identical), SFMBT1 (27% identical), SFMBT2 (25% identical), L3MBTL4 (20% identical), L3MBTL1 (19% identical), L3MBTL3 (19% identical), L3MBTL2 (17% identical), MBTD1 (15% identical), PHC2 (15% identical), PHC3 (15% identical), PHC1 (14% identical), and 6 more.
Diseases named in the same sentence as SCMH1 in open-access papers:
SCMH1 is named in the same sentence as 14 diseases in open-access papers, as found by Europe PMC text mining. Sharing a sentence is not in itself a finding about the gene and the disease. The quoted sentences say what the papers report.
Stroke (4 papers, 2023 to 2024). Sudden impairment of blood flow to a part of the brain due to occlusion or rupture of an artery to the brain. "In addition, circRNA SCMH1 could significantly improve the functional recovery of stroke animal models by enhancing neuroplasticity, and inhibiting glial responsiveness and peripheral immune cell infiltration." (PMID 37664885, 2024). "However, whether circular RNA SCMH1 (circSCMH1) promotes vascular repair by m6A methylation after stroke remains to be elucidated." (PMID 36717587, 2023).
ischemic stroke (3 papers, 2021 to 2026). A stroke disorder caused by obstruction of blood flow to the brain, due to thrombotic (local blood clot formation) or embolic (due to a blood clot or other material traveling from another site) event. "Yang L's team proved that, unlike ceRNA mechanism, circRNA SCMH1 bound to methyl‐CpG‐binding protein 2 (MeCP 2) to upregulate downstream genes, promoting neuronal plasticity and alleviating ischemic stroke." (PMID 37186176, 2023). "A recent article demonstrated that circRNA SCMH1 could be delivered via the extracellular vesicle to alleviate ischemic stroke in rodent and non-human primate models." (PMID 34595165, 2021).
breast carcinoma (1 paper, 2021). "Very recently, a circRNA derived from SCMH1 (hsa_circ_0011946, circ-SCMH1) has been declared to be highly expressed in human cancers, such as breast cancer, hepatocellular carcinoma, and OSCC." (PMID 34353342, 2021). "The suppressive effect of circ-SCMH1 on cell proliferation, epithelial–mesenchymal transition (EMT), and migration/invasion was also found in breast cancer and hepatocellular carcinoma cells." (PMID 34353342, 2021).
diabetes (1 paper, 2013). "There was a small (median differences = 0.01-0.04) but highly significant increase of DNA methylation in females compared to males in FBXL5 and CACYBP (p < 1.00E-04) and a trend towards significance for SCMH1 (p = 0.07), in the diabetes study where samples of both sexes were included." (PMID 23356856, 2013).
lymph node metastasis (1 paper, 2021). "Circ-SCMH1 expression was associated with TNM grade and lymph node metastasis of OSCC patients." (PMID 34353342, 2021).
male infertility (1 paper, 2020). The inability of the male to effect fertilization of an ovum after a specified period of unprotected intercourse. "Skeletal abnormalities and male infertility were observed in mutant mice lacking the Scmh1 SPM domain." (PMID 32719712, 2020).
oral cancer (1 paper, 2022). "Circ-SCMH1 was overexpressed in Cisplatin-resistant OSCC tissues and cells.Circ-SCMH1 contribute to oral cancer development by inhibition of apoptosis in OSCC cells through regulating miR-338-3p/LIN28B." (PMID 35898889, 2022).
cancer (3 papers, 2021 to 2025). A tumor composed of atypical neoplastic, often pleomorphic cells that invade other tissues. "Other studies about circRNA SCMH1 were mainly in cancers, results of which showed that this circRNA was upregulated in cancer cells and might have the ability to promote cell proliferation in various cancer cells." (PMID 37186176, 2023). "We also identified the top 1 GEAR in individual cancer types, such as TLL1 (BLCA), PGK1 (BRCA), RFXANK (CESC), DPP7 (COAD), VWA8 (KIRC), SCMH1 (LGG), HILPDA (LIHC), TLE1 (LUAD), CD151 (LUSC), ANKRD13A (OV), SOCS2 (PAAD), DRG2 (PRAD), ADAMTS6 (STAD), PSMB8 (THCA), ASS1 (UCEC)." (PMID 41404730, 2025).
tumor (2 papers, 2014 to 2021). "This outcome suggested a suppressive role of circ-SCMH1 deficiency in tumor growth and chemoresistance in DDP-resistant OSCC cells in vivo by modulating miR-338-3p and LIN28B." (PMID 34353342, 2021). "Moreover, level of circ-SCMH1 was 6.6-fold higher in DDP-resistant OSCC tumor tissues than that in DDP-sensitive ones." (PMID 34353342, 2021). "Moreover, interfering circ-SCMH1 retarded tumor growth of SCC-15/DDP cells in vivo with DDP treatment or not." (PMID 34353342, 2021).
SCMH1 also shares sentences with these, for which no sentence is quoted: Angelman syndrome (1 paper); hepatocellular carcinoma (1); medulloblastoma (1); oral squamous cell carcinoma (1); Turner syndrome (1).